ARF1 (ARF GTPase 1)
Diseases named in the same sentence as ARF1 in open-access papers (continued):
Sharing a sentence is not in itself a finding about the gene and the disease.
tumor (continued). "By forming a complex with ARF1, IQGAP1 activates the ERK signaling pathway, which enhances tumor cell invasiveness and confers resistance to BRAFV600E inhibitors, such as vemurafenib." (PMID 41035668, 2025). "Genes such as ARF1, SLC25A5, and CDKN2A were significantly up-regulated in tumor samples, while genes such as SNCA, PRNP, and GLS were significantly down-regulated in tumor samples." (PMID 36980514, 2023). "To determine the clinical significance of ARF1, we analyzed ARF1 expression in 20 pairs of CRC tumor tissues and adjacent normal tissues by Western blotting." (PMID 33408784, 2021). "The majority of tumor cases had a stronger expression of ARF1 (65%) and ARF1-GTP (60%) than adjacent normal tissues, with a positive ARF1-GTP correlation with p-ERK expression." (PMID 33408784, 2021). "In the present study, we demonstrated that Arf1 inhibition resulted in lipid droplet accumulation, mitochondrial defects, ER stress, induction of DAMPs (Calr, ATP, HMGB1), and anti-tumor immune responses." (PMID 31924786, 2020). "To functionally confirm that the anti-tumor effects of Arf1-depletion in Lgr5/Apc and MYC-ON mice were indeed dependent on the observed adaptive immune response, we depleted the T lymphocytes after tumor formation by injecting anti-CD4 or anti-CD8 antibodies." (PMID 31924786, 2020). "So far, work on mammalian PSDs has revealed functions for C-terminal domains in regulating ARF6, ARF1 or ARL14 during actin cytoskeletal reorganisation and membrane ruffling, tumour formation, axon regeneration and immune regulation." (PMID 31718774, 2019). "Using orthotopic injection of ARF1 knockdown tumor cells into the mammary fat pads of SCID/beige mice, we show that ARF1 is required for primary tumor growth." (PMID 26908458, 2016). "We also demonstrate that ARF1 and ARF6 control major processes that increase tumor metastasis in vivo such as cell motility, migration, proliferation, and resistance to apoptosis." (PMID 26908458, 2016). "In conclusion, IQGAP1 mediates tumor drug resistance through multiple mechanisms, including the suppression of ferroptosis via YAP activation, ROS-induced Src/FAK signaling, sustained MAPK activation, and ARF1-IQGAP1 complex-driven ERK activation." (PMID 41035668, 2025). "Another pathway does not involve the Rag-dependent form as glutamine in tumor cells can regulate mTORC1 via ADP-ribosylation factor 1(Arf1)." (PMID 38172980, 2024). "Targeting Arf1, LPE, or PPARγ may be a feasible new strategy to promote T-cell infiltration in tumors and improve tumor immunotherapy." (PMID 39872623, 2023). "This information together suggests that inhibition of the Arf1-mediated lipid metabolic pathway in tumor cells has the effect of “one stone killing two birds”, that is, it not only kills CSCs but also alternates TME and activates systemic anti-tumor immunity." (PMID 39872623, 2023). "Indeed, a recent article highlights that the knockdown of Arf-1-mediated metabolism pathway mediates CSC death and induces a tumor-specific immune response." (PMID 35406621, 2022). "ARF1-knockdown stable cell lines, HT29-shARF#1 and HT29-shARF#2 as well as DLD1-shARF1#1 and DLD1-shARF1#2, were subcutaneously injected into flanks of nude mice to establish tumor xenografts, and the tumor volumes were monitored." (PMID 33408784, 2021). "To confirm whether the tumor cell‐derived DNAs truly entered into the co‐cultured DCs or not, we extracted DNAs from the cytoplasm of either the Arf1‐ablation‐stimulated or control DCs." (PMID 37786300, 2023). "To further assess whether PE participated in Arf1 ablation-­induced tumor suppression or not, we generated tumor cells with CTP:phosphoethanolamine cytidylyltransferase (PCYT2) knockdown, which catalyzes the synthesis of PE from ethanolamine." (PMID 39872623, 2023).
tumor (continued). "Moreover, we observed more apoptosis‐associated speck‐like protein containing a caspase recruitment domain (ASC) specks in the Arf1‐ablation‐stimulated DCs than those in the control DCs, indicating more effective activation of ASC by the Arf1‐ablated tumor cells." (PMID 37786300, 2023). "In addition, rabeprazole failed to suppress tumor growth or affect the immune response in ARF1-knockdown CT26 transplanted tumor model." (PMID 37452028, 2023). "To test this hypothesis, we subcutaneously inoculated BALB/c mice with the control or Arf1‐ablated CT26 cells, and then administrated mice with anti‐IFNAR1 and anti‐IL‐1β antibodies or isotype control antibodies at day 0, 2, and 4 after tumor cell injection, respectively." (PMID 37786300, 2023). "We examined whether NF-κB regulated the transcription of CCL5 or not in tumor cells with Arf1 inhibitor treatment or Arf1 knockdown, and found that inhibiting Arf1 significantly upregulated the phosphorylation level of p65 protein (p-p65) in CT26 cells." (PMID 39872623, 2023). "To examine whether DAMPs are essential for the anti-tumor immune response of Arf1 ablation, we first interfered with the action of ATP and HMGB1 in Lgr5/Arf1/Apc intestinal CSC mice by administering ARL61756 (ARL), oxATP, suramin, and the Toll-like receptor 4 (TLR4) inhibitor." (PMID 31924786, 2020). "We found ARF1 to be significantly higher in the WT tumor proteome (ARF1↑WT; no peptides/PSM in G12V vs. 10 peptides and 137 PSM in WT), which might represent an EGFR-independent activation of the RAS/MEK/ERK pathway and a potential escape mechanism for anti-EGFR therapy." (PMID 31805664, 2019). "However, whether ARF1 is important for tumor progression, in vivo, has never been examined." (PMID 26908458, 2016). "We treated either shScram-treated or shCCL5-treated CT26 allografts with the Arf1 inhibitors and found that DU102 could robustly suppress tumor growth of the shScram-treated CT26 allografts but not the shCCL5-treated CT26 allografts." (PMID 39872623, 2023).
infection (31 papers, 2006 to 2025). The state of being infected such as from the introduction of a foreign agent such as serum, vaccine, antigenic substance or organism. "ARF1 is involved in infection by plant pathogens, and membrane modulation by ARF1 complex capture of host cells facilitates pathogenic invasion in both plants and humans." (PMID 35043172, 2022). "However, our study also revealed that the contribution of Arf1 and Arf6 is most likely associated with the earliest stages of infection, either in terms of virion entry or the establishment of infection." (PMID 34440611, 2021). "However, our study also revealed that the contribution of Arf1 and Arf6 is most likely associated with the earliest stages of infection, either during virion entry or during the establishment of infection." (PMID 34440611, 2021). "This indicates that while Asrij and ARF1 function in the hematopoietic system is essential for regulating the immune response, ARF1 depletion from other organs may deteriorate the overall health of the flies and make them more susceptible to infection." (PMID 28273919, 2017). "As we observed increased recruitment of peroxisomes to SCVs after infection and SseI binds to ARF1, we looked closely at the organellar PIP2 level." (PMID 39695325, 2025). "We observed an increase in the activated ARF1 level on peroxisomes after infection with wild-type STM." (PMID 39695325, 2025). "To interrogate the functional role of these host proteins during the P. berghei liver stage infection, we used two pooled siRNAs to knockdown mRNA expression of Arf1, Arf4, and GBF1 in HuH7 cells infected with luciferase-expressing P. berghei (Pb-Luc)." (PMID 38349168, 2024). "Next, we evaluated GII.4 infection in the presence of an Arf1 inhibitor, Golgicide A (GCA), and found that GCA significantly inhibited GII.4 replication (65–75%) at 24 h." (PMID 36854760, 2023). "Our results, together with those of others, reveal that ARF1 utilizes distinct means to target different endomembrane recruitment for conferring advantages for viral replication and infection." (PMID 36091067, 2022). "Here, we demonstrated the function of different GBF1 truncation mutants in CSFV infection and found that CSFV utilized ARF1 in a GBF1 Sec7 domain-dependent manner for infection." (PMID 35044210, 2022). "The endogenous expression level and membrane recruitment of Arf1 and Arf3 was relatively low in Balb 3T3 cells immediately after infection (0 hpi), which was similar to the uninfected cells." (PMID 34440611, 2021). "Altogether, these data suggest that Arf1 and Arf6 are essential for the establishment of infection in the steps before the MCMV genome enters into the nucleus." (PMID 34440611, 2021). "More recent studies have shown that the amount of activated ARF1-GTP gradually increases as infection progresses, and that ARF1 locates to the RC in PV-infected cells." (PMID 33799649, 2021). "As the infection progresses, the concentration of RhoA on the inclusion membrane increases, further inhibiting ARF1 activation." (PMID 34903051, 2021). "This concept is supported by the fact that each GTPase is activated at specific times during infection: 16 hpi for ARF1 and 32 hpi for RhoA." (PMID 34903051, 2021). "Upon infection of the dually labeled D. discoideum strain with L. pneumophila JR32, both 2×PHFAPP-mCherry and Arf1-GFP associated with LCVs in a sustained manner, but the two probes did not strictly overlap and showed distinct accumulation kinetics." (PMID 30538188, 2018). "We compared the changes to Arf1, GBF1, and PI4KB localization caused by 3CD to corresponding changes caused by infection." (PMID 29782554, 2018). "Introduction of Drosomycin-GFP or Defensin-GFP reporter in ARF1 knockdown or in asrij null or asrij knockdown background respectively was assayed after infection with B. subtilis." (PMID 28273919, 2017). "AMP transcript level changes upon ARF1 or Asrij depletion also correspond to reporter-AMP levels seen after infection." (PMID 28273919, 2017).
infection (continued). "ARF1 and Asrij mutants show reduced survival and lifespan upon infection, indicating perturbed immune homeostasis." (PMID 28273919, 2017). "We observed increased levels of ARF1-GTP upon infection with WT Chlamydia and significantly reduced levels of ARF-GTP in CT813 KO-infected lysates (KO versus WT)." (PMID 28465429, 2017). "Altogether, these data indicate that the aromatic cluster functions as a membrane sensor in vivo and that it drives the timing of Arf1 activation during infection in accordance with the ratio between aromatic and positively charged residues." (PMID 24244168, 2013). "To examine this possibility, we depleted endogenous Arf1 by transfecting a pool of three specific siRNAs against Arf1 72 hr prior to infection with WT Salmonella and quantification of pathogen invasion." (PMID 22341462, 2012). "Arf1-GFP recruitment to the LCV increased over the first 2 hours of infection with Legionella producing LpRalF, and Arf1-GFP staining of the LCV remained high until at least 4 hours post-infection." (PMID 23166491, 2012). "As GAT can bind multiple Arf isoforms, we sought to confirm that Arf1 localizes to membrane ruffles induced by Salmonella by performing the same infection with HeLa cells expressing Arf1RFP, which behaves indistinguishably from endogenous Arf1 in cells." (PMID 22341462, 2012). "We observed that GBF1 and Arf1 have little overlap at the inclusion membrane during infection even though they extensively colocalize at the Golgi surrounding the inclusion." (PMID 21909260, 2011). "Infection of either primary human or melan-Ink4a-Arf1 melanocytes with shATF2 markedly increased MITF transcription and protein expression." (PMID 21203491, 2010). "To determine whether host GEF activity would regulate Arf1 internalization later in infection, we treated Tg-mCh-infected cells with DMSO, GCA, or BFA from 29 to 32 hpi." (PMID 38349168, 2024). "During the infection of macrophages by Yersinia pestis, Rab1b recruitment to the Yersinia-containing vacuole directly inhibits phagosome maturation; active Rab1b stabilizes Arf1 on Golgi membranes, and Rab1b is required for GBF1 membrane association." (PMID 38169281, 2024). "By contrast, P. berghei did not associate with Arf1 during the infection of hepatocytes indicating it is not recruited by all apicomplexans." (PMID 38349168, 2024). "To focus our efforts on Arf1, we asked whether endogenous Arf1 expression levels changed during Tg-mCh infection." (PMID 38349168, 2024). "Recent research has shown that ARF1 has a role in viral replication and infection." (PMID 36091067, 2022). "However, the suppression of Arf1 and Arf6 also inhibited the establishment of infection, suggesting that these GTPases are also involved in the earliest stages of infection." (PMID 36077391, 2022). "The increased amount of Arf1 was already detected 2 h post-infection (hpi), as demonstrated by the representative Western blot, and it was maintained throughout the entire early phase, up to the 16th hour of infection." (PMID 34440611, 2021). "However, knockdown of Arf1 and Arf6 affected the earlier stages of infection, prior expression of MCMV immediate early genes, indicating that they are essential for virus entry or transport to the cell nucleus." (PMID 34440611, 2021). "Depletion of ARF1 is likely to impact the morphology of virus-containing compartments and the recycling of internalized virus to the cell surface, which in turn reduces the accumulation of virus at the VS and therefore trans-infection." (PMID 32075937, 2020). "Given its ubiquitous expression, ARF1 may also mediate its effect through other interactors that are involved in responding to infection." (PMID 28273919, 2017). "Hence we tested the effect of Asrij or ARF1 depletion on the ability of flies to combat infection and survive." (PMID 28273919, 2017). "Similarly, the localization coefficient between ARF1 and 3A are less than 0.3 at 4, 6, and 8 hrs post-infection." (PMID 28303920, 2017).
infection (continued). "Further, we also tested whether ARF1 depletion in the hemocyte compartment specifically or in other organs like trachea has any effect on the survival of the flies post infection." (PMID 28273919, 2017). "Upon infection with E. coli, flies depleted of ARF1 or Asrij, both showed compromised survival." (PMID 28273919, 2017). "Both LpRalF constructs were equally efficient at recruiting Arf1 one hour after infection." (PMID 24244168, 2013). "RalF is essential for the recruitment of Arf1 to the LCV during infection." (PMID 23166491, 2012). "The difference in LpRalF and RpRalF localization mediated by the capping domain suggested that the two proteins would differ in their abilities to mediate recruitment of Arf1 to the vacuole containing Legionella when delivered by the Dot/Icm system during infection." (PMID 23166491, 2012). "To confirm our observation that BFA inhibits MHV replication but also to prove that the effects of this drug are due to the inhibition of GEF activities, we next analyzed to what extent the expression of a dominant-negative mutant of ARF1 (T31N) would affect MHV infection." (PMID 18551169, 2008). "However the mechanism that ARF1 is involved in the infection and replication of aquatic animal viruses remains unclear." (PMID 36091067, 2022). "However, the knockdown of Arf1 and Arf6 also abolished the establishment of infection." (PMID 34440611, 2021). "Also, the flies depleted of ARF1 in the hemocyte compartment have reduced survival post-infection." (PMID 28273919, 2017). "Further, infection with WT STM activated ARF1 more when compared to the ΔsseI strain, while the total ARF1 levels remained unchanged." (PMID 39695325, 2025). "To further explore the role of GBF1 during infection, we employed the well-characterized chemical inhibitor golgicide A (GCA) to selectively decrease GBF1-mediated Arf1 activation." (PMID 38349168, 2024). "To confirm the essential role of Arf1 in the replication of the BFA-resistant mutant, we analyzed the infection of the wt poliovirus and a virus with the reconstructed BFA-resistant mutations in 2C (2C/59) in Arf1 KO cells." (PMID 37721955, 2023). "Here, we found that grass carp ARF1 (gcARF1) can promote GCRV replication and infection, which is dependent on the GTPase activity of ARF1." (PMID 36091067, 2022). "In conclusion, our study demonstrates a significant role of Arf1, Arf3, Arf4, and Arf6 in the pathogenesis of CMV infection and host cell reorganization during the early phase of infection." (PMID 34440611, 2021). "We also demonstrated that InaC directly interacts with the host small GTPases ARF1 and ARF4 to control the formation of PTM-MTs and, consequently, the dispersal of Golgi ministacks around the inclusion during infection." (PMID 34903051, 2021). "In the context of infection, HIV-1 ability to mediate the downregulation of MHC-1 is achieved by targeting AP-1 and ARF1 activity, resulting in the accumulation of MHC-1 in the TGN or endosomes." (PMID 32075937, 2020). "Taken together, these data suggest that trafficking of CD81 and p24 Gag to the cell periphery to form the TEM is compromised by knockdown of ARF1, BIN-1, RAB7L1, and RAB8A, potentially preventing the efficient trans-infection of virus via the VS." (PMID 32075937, 2020). "We show that ADP-ribosylation factor 1 (ARF1), bridging integrator 1 (BIN1), and Rab GTPases RAB7L1 and RAB8A are important regulators of HIV-1 trafficking to the VS and therefore the infection of CD4+ T cells." (PMID 32075937, 2020).